EMC3 (ER membrane protein complex subunit 3)
Description:
Part of the endoplasmic reticulum membrane protein complex (EMC) that enables the energy-independent insertion into endoplasmic reticulum membranes of newly synthesized membrane proteins. Preferentially accommodates proteins with transmembrane domains that are weakly hydrophobic or contain destabilizing features such as charged and aromatic residues. Involved in the cotranslational insertion of multi-pass membrane proteins in which stop-transfer membrane-anchor sequences become ER membrane spanning helices. It is also required for the post-translational insertion of tail-anchored/TA proteins in endoplasmic reticulum membranes. By mediating the proper cotranslational insertion of N-terminal transmembrane domains in an N-exo topology, with translocated N-terminus in the lumen of the ER, controls the topology of multi-pass membrane proteins like the G protein-coupled receptors. By regulating the insertion of various proteins in membranes, it is indirectly involved in many cellular processes (Probable).
Synonyms: TMEM111; POB
Tractability: Small molecule: a structure with a bound ligand is known. Antibody: UniProt predicts a signal peptide or a membrane-spanning region. PROTAC: ubiquitination databases record sites on it; its protein half-life has been measured.
Gene: Protein-coding gene on chromosome 3 (9,962,682 to 10,011,202, reverse strand). Ensembl gene ENSG00000125037.
Subcellular location: Endoplasmic reticulum membrane
Pathways (Reactome):
Signal Transduction: RHOA GTPase cycle
Gene Ontology:
Molecular function: membrane insertase activity; protein binding
Biological process: protein insertion into ER membrane by stop-transfer membrane-anchor sequence; tail-anchored membrane protein insertion into ER membrane
Cellular component: EMC complex; endoplasmic reticulum membrane; membrane
Genetic constraint (gnomAD): Loss-of-function variants: 11 observed, 33.21 expected, observed/expected ratio (o/e) 0.33, 90% interval 0.21 to 0.55. The upper end of that interval is the gene's LOEUF score, 0.55, which puts it in group 2 of 6, group 1 being the genes least tolerant of losing a copy. Missense variants: 189 observed, 290.54 expected, observed/expected ratio (o/e) 0.65, 90% interval 0.58 to 0.73. Synonymous variants: 111 observed, 105.94 expected, observed/expected ratio (o/e) 1.05, 90% interval 0.9 to 1.23.
Homologues: Orthologues: chimpanzee EMC3 (100% identical), dog EMC3 (100% identical), macaque EMC3 (100% identical), mouse Emc3 (99% identical), pig EMC3 (99% identical), rat Emc3 (99% identical), guinea pig EMC3 (99% identical), tropical clawed frog emc3 (94% identical), zebrafish emc3 (90% identical), Drosophila melanogaster EMC3 (59% identical), Caenorhabditis elegans emc-3 (52% identical).
Diseases named in the same sentence as EMC3 in open-access papers:
EMC3 is named in the same sentence as 17 diseases in open-access papers, as found by Europe PMC text mining. Sharing a sentence is not in itself a finding about the gene and the disease. The quoted sentences say what the papers report.
breast carcinoma (1 paper, 2022). "Top-ranked Stem.Sig genes, such as EMC3, BECN1, VPS35, and PCBP2, showed improved immune response after knockout in melanoma, renal carcinoma, breast carcinoma, and colon adenocarcinoma from multiple CRISPR datasets." (PMID 35488273, 2022).
colitis (1 paper, 2021). Inflammation of the colon. "Emc3-deficient mice are more susceptible to DSS-induced colitis and Salmonella Typhimurium infection." (PMID 33785873, 2021). "H&E staining of colonic sections showed an extensive loss of crypts in mutant mice, and pathological analysis further confirmed Emc3-deficient mice were more susceptible to DSS-induced colitis." (PMID 33785873, 2021). "However, spontaneous inflammation in Emc3ΔIEC colon was remarkably reduced after antibiotics treatment, illustrating the association of colitis with bacteria dysbiosis after Emc3 depletion." (PMID 33785873, 2021). "Collectively, we demonstrate that intestinal epithelial Emc3 plays a protective role against colitis and pathogen infection." (PMID 33785873, 2021). "Deletion of Emc3 in intestinal epithelium decreases mucus production by goblet cells and Paneth cell population, along with gut microbial dysbiosis, which result in spontaneous inflammation and increased susceptibility to DSS-induced colitis." (PMID 33785873, 2021). "Next, we evaluated whether Emc3 played a protective role against DSS-induced colitis." (PMID 33785873, 2021).
epilepsy (1 paper, 2022). A brain disorder characterized by episodes of abnormally increased neuronal discharge resulting in transient episodes of sensory or motor neurological dysfunction, or psychic dysfunction. "Moreover, among ten EMC subunits, EMC3 and EMC6 have the most prominent effect, and overexpression of EMC3 or EMC6 is sufficient to restore the function of epilepsy-associated GABAA receptor variants." (PMID 35938049, 2022).
lung disease (1 paper, 2024). "Amelioration of both the alveolar simplification and mitochondrial dysfunction associated with SFTPCI73T by deletion or inhibition of EMC3 or VCP identifies these pathways for development of pharmacological therapy of SFTPCI73T-associated lung disease." (PMID 39405113, 2024).
retinal degeneration (1 paper, 2020). Degeneration of the retina. "Furthermore, knocking out the Emc3 gene in mammalian rod photoreceptor cells led to dysregulated rhodopsin trafficking and retinal degeneration, as seen in flies, suggesting that EMC function is conserved in mammals." (PMID 31263175, 2020).
virus infection (1 paper, 2016). "In fact, our data suggest that other EMC subunits, particularly EMC3, EMC4, EMC5, EMC6, EMC7, and EMC10, may also exert roles in supporting virus infection." (PMID 28012275, 2016).
tumor (2 papers, 2017 to 2024). "According to our data, losses of EMC3 (33/48 ccRCC genomes) at 3p25.3 preceded in number losses of VHL 16/48 ccRCC tumour at that locus." (PMID 28486536, 2017).
bacterial infection (1 paper, 2021). "Together, our study shows that Emc3 is required for intestinal homeostasis and has a protective role against inflammation and bacterial infection." (PMID 33785873, 2021).
EMC3 also shares sentences with these, for which no sentence is quoted: colon adenocarcinoma (1 paper); folliculitis (1); infection (1); interstitial lung disease (1); melanoma (1); pheochromocytoma (1); renal carcinoma (1); respiratory failure (1); retinal angiomas (1).